BCL2L2-PABPN1 (BCL2L2-PABPN1 readthrough)
Description:
Promotes cell survival. Blocks dexamethasone-induced apoptosis. Mediates survival of postmitotic Sertoli cells by suppressing death-promoting activity of BAX.
Target class: Other cytosolic protein
Gene: Protein-coding gene on chromosome 14 (23,306,833 to 23,326,175, forward strand). Ensembl gene ENSG00000258643.
Subcellular location: Mitochondrion membrane
Subcellular location (Human Protein Atlas): Nucleoplasm; Nuclear speckles
Gene Ontology:
Molecular function: disordered domain specific binding; identical protein binding; protein binding; channel activity
Biological process: negative regulation of apoptotic process; regulation of apoptotic process; extrinsic apoptotic signaling pathway in absence of ligand; intrinsic apoptotic signaling pathway in response to DNA damage; positive regulation of apoptotic process; release of cytochrome c from mitochondria; spermatogenesis; developmental process involved in reproduction; transmembrane transport
Cellular component: Bcl-2 family protein complex; mitochondrion; mitochondrial outer membrane; cytosol; mitochondrial membrane
Genetic constraint (gnomAD): Loss-of-function variants: 9 observed, 39.07 expected, observed/expected ratio (o/e) 0.23, 90% interval 0.14 to 0.4. The upper end of that interval is the gene's LOEUF score, 0.4, which puts it in group 1 of 6, group 1 being the genes least tolerant of losing a copy. Missense variants: 289 observed, 451.89 expected, observed/expected ratio (o/e) 0.64, 90% interval 0.58 to 0.7. Synonymous variants: 167 observed, 165.5 expected, observed/expected ratio (o/e) 1.01, 90% interval 0.89 to 1.15.